TET1 (tet methylcytosine dioxygenase 1)
Diseases named in the same sentence as TET1 in open-access papers (continued):
Sharing a sentence is not in itself a finding about the gene and the disease.
cancer (continued). "Ten–eleven translocation protein 1 (TET1) functions as an epigenetic regulatory molecule, mediating the majority of DNA demethylation, and plays a role in the development of different types of cancers by regulating the expression of proto‐oncogenes and oncogenes." (PMID 39477806, 2024). "However, the role of TET1 in cancer metabolism remains poorly understood." (PMID 38929174, 2024). "Thus, the functional spectrum of TET1 in human cancer remains to be fully defined." (PMID 37020036, 2023). "Previous studies have observed Aza-induced hypermethylation in the cancer genome and attributed this phenomenon to a transient alteration in gene transcription reflecting the immediate response of cells to perturbation, or downregulated activity of TET1, a demethylating enzyme." (PMID 37305656, 2023). "Notably, TET1 is preserved in its entirety in most cancers without undergoing mutations, unlike TET2, which frequently undergoes somatic mutations." (PMID 38003566, 2023). "In agreement with this view, a TET1 isoform that lacks regulatory domains, including its DNA-binding domain, but retains its catalytic activity, is enriched in cancer cells, suggesting that mistargeted TET activity may drive oncogenic events, such as genomic instability." (PMID 35191837, 2022). "Also, in a recent study, TET1 was shown to maintain cancer stem cells in TNBC." (PMID 35646706, 2022). "Based on the increased levels of 5mC oxidation products in cancer cells that express Tet1s and on our previous findings that Tet1-CD overexpression results in a significant increase of 5mC oxidation, we addressed the catalytic activity of Tet1s compared to full-length Tet1." (PMID 36056023, 2022). "Additionally, the downregulation of TET1 was reported to occur at the early stage and its expression could inhibit the proliferation of cancer cells in CRC." (PMID 34957093, 2021). "Indeed, the multiple cancer cell lines studied, including nasopharyngeal, esophageal, lung, gastric, colon, breast, cervical, and renal carcinomas, as well as lymphomas, showed high frequency TET1 promoter methylation and silencing." (PMID 34209564, 2021). "However, the TET1 was poorly expressed in HeLa cells in contrast to other cancer cells." (PMID 34489496, 2021). "Of note, TET1 promoter methylation was also detected in primary tumors for the same cancer types as the cancer cell lines, but less frequently than in cell lines, which emphasizes the importance of microenvironment and cellular context in the regulation of TET1." (PMID 34209564, 2021). "Thus, our study indicated that TET1 could be a promising target for overcoming chemoresistance in cancer." (PMID 30784212, 2019). "This study yields a comprehensive genome-wide view of TET-targeted loci in human cancer cells, revealing for the first time loci that are particularly susceptible to TET-regulated cytosine modifications and identification of distinct and overlapping functions of TET1, TET2, and TET3." (PMID 24958354, 2014). "To further explore the impact of GATA6 and TET1 on CAF function, we conducted scratch and transwell assays to evaluate their effect on cancer cell migration and invasion." (PMID 40216762, 2025). "Unique chromosomal translocations involving TET1 and mixed lineage leukemia (MLL) have been identified in certain cancers, further implicating TET proteins in oncogenic pathways." (PMID 40663150, 2025). "TET1/FOXO4 Axis: CRISPR-induced TET1 overexpression sequesters β-catenin in the cytoplasm, inhibiting Wnt signaling while stabilizing FOXO4 to regulate cancer stem cell (CSC) properties and EMT processes." (PMID 40951343, 2025). "For instance, TET1 can activate PTEN by promoter CpG demethylation and 5hmC accumulation, thereby suppressing cancer cell invasion." (PMID 41165593, 2025).
cancer (continued). "Studies found that TET1 upregulated TAR DNA-binding protein (TARDBP) and enhanced the function of obesity-driven cancer stem cells in triple-negative breast cancer (TNBC)." (PMID 40014756, 2025). "DNA methylation or demethylation in cancer is regulated by DNA methyltransferases (DMNTs), which include DMNT1, DMNT3A, and DMNT3B, and the ten-eleven translocation (TET) enzymes TET1, TET2, and TET3, which are known for their roles in cancer." (PMID 38566132, 2024). "The expression of TET1, TET2, and TET3 positively correlated in pan-cancer, with a stronger positive correlation observed between TET2 and TET3." (PMID 39104395, 2024). "Elevated TET1 expression correlates with worse outcomes in solid organ tumors such as ACC, KIRP, LIHC, and SARC, yet it signifies better prognoses in LGG and THYM cancers." (PMID 39104395, 2024). "TET1 gene exhibited high methylation levels, whereas TET2 and TET3 genes displayed hypomethylation in most cancers, which correlated closely with patient prognosis." (PMID 39104395, 2024). "The results depicted in the Boxplot revealed that the expression level of the TET3 gene ranked highest across pan-cancer samples, followed by TET2, with TET1 exhibiting the lowest expression." (PMID 39104395, 2024). "In this study, we assessed TET1 and Wnt1 expression in 5-azacytidine-treated HT29 cells, a demethylating agent commonly used in cancer therapy." (PMID 39495308, 2024). "In 2022, it was discovered that FMRP serves as an m5C reader, acting as a coordinator between the m5C writer TRDMT1 and eraser ten-eleven translocation 1 (TET1), and this coordination facilitates mRNA-dependent repair and cell survival in cancer." (PMID 39340806, 2024). "The inhibition of the proliferation of healthy primary fibroblasts induced by the overexpression of TET1 and TET2 is in agreement with the results of studies on various cancer cell lines." (PMID 37371754, 2023). "Compared to other genes (TET1 and TET2) in the TET family, the functions of TET3 in human cancer remains limited." (PMID 35757739, 2022). "TET1 and TET2 activities are also downregulated in several types of cancer by XPO1-mediated nuclear exportation, which can be restored by the XPO1 inhibitor leptomycin B (LMB)." (PMID 36203205, 2022). "TET1 has been reported both as an oncogene and a TSG in human cancers, where its epigenetic inactivation has been demonstrated." (PMID 36278182, 2022). "Results indicate that TET1 and TET3 gene and protein expression was cell-specific in cancer cell-lines." (PMID 35372016, 2022). "Detailed analysis demonstrated that Tet1 antagonizes Tet2 in the regulation of HSC self-renewal and malignant myeloid development but compensates for Tet2 in preventing B and T lymphocytic malignancies." (PMID 36203205, 2022). "The induction of TET1 protein coactivates HIF1α and HIF2α to enhance their transcriptional activity independent of its enzymatic activity, which leads to EMT and cancer cell invasion." (PMID 32528872, 2020). "In this paper, we investigated the effect of mutations on DNA methylation modification genes such as DNMT1, DNMT3A, MBD1, MBD4, TET1, TET2, and TET3 through a pan-cancer analysis." (PMID 32093698, 2020). "As eraser regulators in 5mC methylation, ten-eleven translocation enzymes (TET1, TET2, and TET3) are often downregulated in cancer-inducing DNA demethylation by converting 5mC to 5-hydroxymethylcytosine (5hmC)." (PMID 33195409, 2020). "Among epigenetic genes, DNA methylation related epigenetic modifiers, DNMT1, DNMT3A, MBD1, MBD4, TET1, TET2, and TET3, have been studied related to cancer." (PMID 32093698, 2020). "The downregulation of TET1 and its direct target gene AJAP1 promotes cancer progression via activation of β-catenin signaling." (PMID 32528872, 2020). "The favorable clinical outcomes for TET1-MUT versus TET1-WT were also prominent and consistent across subgroups of age, sex, cancer type, TMB status and drug class (all Pinteraction > 0.05)." (PMID 31623662, 2019).
cancer (continued). "Variation of Ten-Eleven Translocation (TET) proteins (TET1, TET2 and TET3) is common in human cancers." (PMID 31057717, 2019). "In this study based on carefully collected and curated genomic and clinical data, we observed that TET1-MUT was enriched in patients responding to ICIs and strongly predicted clinical benefit across multiple cancer types." (PMID 31623662, 2019). "Strikingly, cancer cell migration increased as a result of DNMT3A-3 L targeting, but decreased by TET1 targeting or overexpression of WNT5B complementary DNA (cDNA)." (PMID 29871649, 2018). "Likewise, in line with anticipated significance of Tet proteins for neuro- and gliogenesis, the aberrantly increased TET1-dependent 5mC oxidation may represent one of the epigenetic signatures of these cancers reflecting their likely neural progenitor/stem cell origin." (PMID 28228863, 2017). "Emerging evidence also suggests that the miR-29 family contributes to epigenetic regulation in cancer and primordial germ cell (PGC) development by targeting TET1, leading to global DNA hypermethylation." (PMID 29254230, 2017). "However, it is unknown whether TET1 can also function as a transcriptional repressor in cancer." (PMID 27116251, 2016). "Knockdown of TET1 induced low expression of PTEN and activation of AKT and FAK pathways, which in turn favored the proliferation, migration and invasion abilities of cancer cells." (PMID 27121319, 2016). "This study represents the first comprehensive genome-wide analysis of the role of TET1, TET2, and TET3 in patterning the distribution of 5mC and 5hmC in human cancer cells." (PMID 24958354, 2014). "Similarly, TET1 depletion reduced CAF survival, marker expression, and ability to drive cancer cell migration/invasion." (PMID 40216762, 2025). "TET1, a member of the TET family, induces DNA demethylation by converting 5-methylcytosine (5mC) to 5-hydroxymethylcytosine (5hmC), and is often downregulated in cancers." (PMID 39334363, 2024). "Firstly, utilizing transcriptome data from 33 tumors available in the UCSC Xena database, we conducted an extraction and analysis of the expression profiles of the target genes belonging to the TET family (specifically, TET1, TET2, and TET3) across various types of cancer." (PMID 39104395, 2024). "Contrary to the concept of the Warburg effect in cancer cells, TET1 increased energy production mainly using OXPHOS rather than using glycolysis." (PMID 38929174, 2024). "In endometrial CSCs, TET1 increases the levels of 5-hmC in the promoter regions of the key CSC marker genes (NANOG, SOX2, and OCT4), thereby enhancing their expression and supporting the cancer stemness." (PMID 38929174, 2024). "In this case, dCas9:TET1 increased BRCA1 expression and inhibited the proliferation of a cancer cell line, highlighting the therapeutic potential of epigenome editing to reduce hypermethylation in promoters of tumor suppressor genes, which is one of the hallmarks of cancer." (PMID 36980849, 2023). "The level of TET1 enzyme, which is responsible for DNA demethylation, was not changed by cancer cell secretion." (PMID 35265687, 2022). "Finally, we reported physical interactions between FOXA1 with TET1 and TET2 both in an in vitro setup and in vivo at physiological levels in MCF-7 cells, adding further support for FOXA1 attracting TET1 and TET2 to induce local demethylation in cancer cells." (PMID 35440061, 2022). "After transfection, the TET1 plasmid but not the empty plasmid increased the protein level of TET1 in hiPSC-CMs, independent of cancer secretions." (PMID 35265687, 2022). "When TET1 was overexpressed (DNA methylation level was reduced) in hiPSC-CMs treated with cancer cell secretion, the peak INa and late INa were not changed." (PMID 35265687, 2022).
cancer (continued). "They demonstrated that knockdown of TET1 inhibited cell growth in vitro and in vivo and induced transcriptome reprogramming, affecting critical signalling pathways in cancer, but this effect was independent of its demethylation activity." (PMID 34656178, 2021). "TET1-mediated demethylation induces a 5hmC increase at the promoter regions of DKK and SFRP genes, which were upstream inhibitors of WNT signaling pathway, hence TET downregulation can lead to cancer growth via repressing these inhibitors of WNT pathway." (PMID 34957093, 2021). "Conversely, the catalytic domain of TET1 DNA-demethylase (TET1cd) fused to dCas9, MS2, Casilio and SunTag can effectively induce demethylation as well as mRNA level increase at hypermethylated targeted genes in mammalian embryonic and cancer cell lines." (PMID 33419220, 2021). "In multiple cancer cell lines and primary tumors, whole genome CpG methylation analysis showed that TET1, but not TET2 or TET3, was downregulated by promoter methylation compared to the normal controls." (PMID 34209564, 2021). "In fact, the canonical TET1 protein (TET1FL) is the only isoform expressed in embryonic stem cells, while the TET1ALT isoform is predominantly expressed in adult cells and is overexpressed in cancers such as breast, uterine, ovarian, AML and glioblastoma." (PMID 34209564, 2021). "Therefore, the effect of HMGA2 in TET1 expression and the subsequent effect of TET1 in HOXA9 expression is known as the HMGA2/TET1/HOXA9 signalling pathway, which has a role in the invasion and metastasis of cancer cells." (PMID 33375038, 2020). "The result that TET1 mRNA was significantly related to overall survival, as well as TET3 and TDG mRNAs were independent prognostic factors for patients, suggests the relationship between DNA methylation and central signaling pathways involved in cancer." (PMID 32375881, 2020). "Therefore, we investigated the effect of mutations on DNA methylation modification genes such as DNMT1, DNMT3A, MBD1, MBD4, TET1, TET2 and TET3 through a pan-cancer analysis." (PMID 32093698, 2020). "TET1, a member of the TET family, induces DNA demethylation and by converting 5-methylcytosine (5mC) to 5-hydroxymethylcytosine (5hmC), and it is often down-regulated in cancers." (PMID 33088215, 2020). "However, its scope of application falls in a pan-cancer setting like MSI-H, thus there would still be substantial patients with TET1-MUT who are most likely to derive clinical benefit from ICI treatment." (PMID 31623662, 2019). "TET1 has been reported to be absent in cancers, and to influence various oncogenes and anti-oncogenes." (PMID 31399111, 2019). "Analyses were here extended to several cancer cell lines and indicated that hypermethylation of TET1 CGI was only able to reduce TET1 transcription without causing complete silencing." (PMID 24939750, 2014). "Accordingly, no paper has reported a complete repression of TET1 in cancer but only its down-regulation." (PMID 24939750, 2014). "Thus, this study uncovers a novel oncogenic mechanism in which TET1 promotes oncogenesis and cancer progression through a non-enzymatic interaction between TET1 and HIF1α in hypoxia, providing novel therapeutic targeting implications for cancer." (PMID 37020036, 2023). "Importantly, the (patho)physiological outcome is not exclusive to cancer cells but is regulated by the abundance of the Tet1 isoforms and their stoichiometry." (PMID 36056023, 2022). "This study demonstrates for the first time that TET1 expression is regulated by DNA methylation during 3-MCA-induced lung carcinogenesis and that TET1-mediated hydroxymethylation regulates the BER pathway and inhibits cancer cell proliferation, migration and invasion." (PMID 34656178, 2021).
cancer (continued). "While TET1 was ectopically expressed by ~35-fold in the TET1-CD overexpression T24 cells, several previously identified TET1 target genes, such as TIMP3 and DKK1 in other cancer types, were also induced at 2.1- and 1.8-fold compared to the control cells (EV), respectively." (PMID 32528872, 2020). "This suggests that under physiological setting, TET1 expression might be negatively regulated by HMGA2 chromatin remodeling factor, leading to increased methylation and silencing of HOXA7/9 —a step which promotes cancer progression." (PMID 31426393, 2019). "However, after adjusted for age, sex, cancer type, and TMB, there was only numerically significant OS benefit (HR = 0.54 [95% CI, 0.27 to 1.11], adjusted P = 0.095), probably due to the limited sample size of the TET1-MUT group (n = 22)." (PMID 31623662, 2019). "Moreover, in the quantitative methylation-specific PCR (Q-MSP) analysis, the normalized methylation value (NMV) for the TET1 and TET3 gene promoters tended to be higher in cancer cells than in normal tonsil samples and normal cell lines (P < 0.001 and P = 0.002, respectively)." (PMID 29849955, 2018). "TET1 can promote CpG islands demethylation in specific genes and often absent in various cancers." (PMID 27121319, 2016). "Moreover, cancer metabolism has been suggested to affect immunometabolism and stem cell metabolism; however, the metabolism in ovarian CSCs, especially in the TET1-reprogrammed stem state, has not yet been investigated." (PMID 38929174, 2024). "Besides, patients with TET1 mutation achieved longer progression-free survival (PFS) and overall survival (OS) after treated by immunotherapy than those without TET1 mutation in various cancers." (PMID 37261523, 2023). "TET1 expression was undetectable in 7 out of the 17 PCs, variable heterogeneous (VH), with areas of positive staining together with areas of negative staining, was seen in 6 carcinomas, and 4 carcinomas showed positive staining in most cells, regardless of strength (+)." (PMID 26973719, 2016). "In contrast, in PCa, TET1 was abundantly expressed exclusively in AMACR-positive cancer cells, whereby not all AMACR-positive cells expressed TET1." (PMID 34844636, 2021). "As TET1-MUT and MSI-H are not substantially overlapped, TET1-MUT is potential to serve as another pan-cancer biomarker to ICI response in addition to MSI-H." (PMID 31623662, 2019).
infection (7 papers, 2017 to 2025). The state of being infected such as from the introduction of a foreign agent such as serum, vaccine, antigenic substance or organism. "In EBi3-/- mice, infection caused an increase in DNA demethylation and analyzing EBi3-/-C versus EBi3-/-I we can see that TET1 plays the major differences observed in S2, but TET2 and TET3 also increased strongly their expression values." (PMID 32078636, 2020). "Our results using tetramers to examine clonal populations of CD8 T cells during infection hint that Tet1/3 deficiency may alter the TCR repertoire or immunodominance during an acute immune response, although further investigations are necessary." (PMID 40175595, 2025). "We performed gRNA lentiviral infection and dCas9-Suntag-TET1 lipofection in PWS iPSCs and then maintained the cells in bulk without single-cell cloning, allowing us to observe the transition dynamics right after transfection." (PMID 41152294, 2025). "Taken together, microbiota promotes the differentiation of ILC1s and suppresses TET1 expression, which is beneficial for resistance to pathogen infection in adult mice." (PMID 38839760, 2024). "To test the role of Tet1/3 in CD8 effector T-cell fates during acute LCMV-Armstrong infection, we challenged RorcCreTg Tet1/3fl/fl mice (hereafter referred to as Tet1/3cDKO), in which double-positive thymocytes and their αβ CD4+ and CD8+ single positive progenies are deficient in Tet1 and Tet3." (PMID 40175595, 2025). "In human chondrocytes, TET1 and TET3 mRNA level were increased by Ad-TWIST1 infection by approximately 2 fold." (PMID 28220902, 2017). "Furthermore, the qRT-PCR analysis demonstrated a significant upregulation of TET1 but not TET2 and TET3 mRNA expression in normal gastric epithelium and GC cells after H. pylori (26695 and SS1) infection (P < 0.0001)." (PMID 37016382, 2023).